SIRT1 (sirtuin 1)
Diseases named in the same sentence as SIRT1 in open-access papers (continued):
Sharing a sentence is not in itself a finding about the gene and the disease.
multiple sclerosis (continued). "For example, Ciriello and his colleagues observed a significant decrease in the level of phosphorylated SIRT1, the active form of SIRT1, in the patients with multiple sclerosis." (PMID 30374331, 2018). "In contrast to SIRT1 overexpression, in an established mouse model of multiple sclerosis, SIRT1 inactivation increased the production of new oligodendrocyte progenitor cells in the adult mouse brain; ameliorated remyelination; and delayed paralysis." (PMID 28197299, 2017). "There are many animal studies, but no studies investigating the role of SIRT1 level and SIRT1 (rs3818292, rs3758391, rs7895833) gene polymorphisms in patients with optic neuritis and multiple sclerosis." (PMID 36949521, 2023). "Studies conducted with SIRT1 rs7895833 are closely related to multiple sclerosis pathogenesis." (PMID 37892107, 2023). "This study is significant because it analyzes SIRT1 rs3818292, rs3758391, and rs7895833, and serum SIRT1 levels in individuals with multiple sclerosis in the Lithuanian population and compares these results with those of healthy control subjects without other diseases, such as optic neuritis." (PMID 37892107, 2023). "Studies on patients with multiple sclerosis showed that SIRT1 increased in damaged brain tissue and SIRT1 decreased in peripheral blood monocytes when multiple sclerosis recurred, suggesting a certain relationship between SIRT1 and the pathogenesis of multiple sclerosis." (PMID 34928817, 2021). "Nanocurcumin capsule and resolvin D1 treatment are associated with decreased miR-145 expression and increased levels of SIRT1 in multiple sclerosis and uveitis, suggesting that miR-145 may be a key regulator of SIRT1." (PMID 33802566, 2021). "In our study, we assessed the effect of microRNAs on the expression level of neuroprotective proteins, including neurotrophins (BDNF and NT4/5), heat shock proteins (HSP70 and HSP27), and sirtuin (SIRT1) in peripheral blood mononuclear cells in the development of multiple sclerosis." (PMID 34202956, 2021). "However, further investigations are necessary to fully delineate the role of SIRT1 in multiple sclerosis." (PMID 23888142, 2013). "Furthermore, through the cytohubba SIRT1 was identified as the hub gene of the multiple sclerosis." (PMID 34928817, 2021). "The aim of this study was to find a link between neurotrophins (BDNF and NT4), SIRT1, heat shock proteins (HSP27 and HSP27), and miRNAs that are involved in the development of multiple sclerosis." (PMID 34202956, 2021). "The aim of this study was to find out a link between neurotrophins (BDNF and NT4/5), SIRT1, heat shock proteins (HSP70 and HSP27), and miRNAs that are involved in the development of multiple sclerosis." (PMID 34202956, 2021). "SIRT1 inhibition with Sirtinol attenuates the neuroprotective effects of SRT501, suggesting a protective role of SIRT1 in multiple sclerosis." (PMID 23888142, 2013). "In a mouse model of multiple sclerosis, experimental autoimmune encephalomyelitis (EAE), SIRT1 activation by SRT501 or SRT1720 maintains axonal density, prevents neuronal loss, and improves neuronal dysfunction." (PMID 23888142, 2013). "We have previously observed that SIRT1 co-localizes with surviving OLGs in multiple sclerosis (MS) plaques, but it is not yet known whether SIRT1 is involved in OLGs survival after exposure to sublytic C5b-9." (PMID 32328069, 2020).
psoriasis (22 papers, 2015 to 2024). An autoimmune condition characterized by red, well-delineated plaques with silvery scales that are usually on the extensor surfaces and scalp. "Other than that, the SIRT1 activator SRT2104 exhibits promise in mitigating psoriasis symptoms by reducing the expression of genes linked to inflammatory responses and skin cell differentiation, which are IL-17 and TNF-α." (PMID 39456475, 2024). "These previous studies underline the importance of SIRT1 in psoriasis treatment." (PMID 38397784, 2024). "Through its ability to modulate the activity of transcription factors like NF-κB and AP-1, which are critical in controlling inflammatory responses, SIRT1 demonstrates anti-inflammatory capabilities and has been linked to guarding against oxidative stress-induced damage in psoriasis." (PMID 39456475, 2024). "In summary, sirtuins, particularly SIRT1, play a significant role in modulating oxidative stress in psoriasis by regulating antioxidant defenses, inhibiting inflammatory pathways, and maintaining redox balance." (PMID 39456475, 2024). "SIRT1 was also related strictly to mitochondrial functions, which, in turn, play a certain role in psoriasis development." (PMID 38397784, 2024). "According to GEO databases, Sirtuin1 (SIRT1) levels significantly decreased in psoriasis patients’ lesion tissues; this was also the case in the IMQ-treated mice, while NMN treatment reversed the SIRT1 decline in the mouse model." (PMID 38397784, 2024). "Dysregulation of sirtuin expression, observed in psoriasis with reductions in some (SIRT1-5) and increases in others (SIRT6, SIRT7), was reported to contribute to oxidative stress and inflammatory processes associated with the condition." (PMID 39456475, 2024). "It was reported that SIRT1 expression in skin biopsy specimens from psoriasis patients was dramatically downregulated." (PMID 38397784, 2024). "In particular, significantly reduced SIRT1 expression in skin samples from patients with psoriasis compared with controls has been noted." (PMID 37445960, 2023). "It is noteworthy that a reduced amount of SIRT1 is also found in the sebaceous glands of patients with psoriasis." (PMID 37445960, 2023). "In fibroblasts from patients with psoriasis, SIRT1 activation has been shown to play an important role in restoring both mitochondrial function and redox balance through modulation of MAPK signalling." (PMID 37445960, 2023). "A trial involving a SIRT1 activator (SRT2104) to treat patients with moderate-to-severe psoriasis has shown promising results with a satisfactory safety profile." (PMID 37445960, 2023). "As SIRT1 endorses keratinocyte differentiation and is able to inhibit keratinocyte proliferation, the decreased expression and activity of SIRT1 in fibroblasts of skin samples from psoriatic plaques suggest that SIRT1 has an important role in psoriasis." (PMID 35883760, 2022). "HDAC1 was overexpressed in psoriasis patients while SIRT1 was decreased in the basal layer of psoriasis patients compared to healthy controls." (PMID 35280995, 2022). "Our data suggested that catalpol inhibited the NF-κB and MAPKs signaling pathways and up-regulated the expression of SIRT1 in the skin of psoriasis-like mice." (PMID 33323018, 2021). "Catalpol inhibits the NF-κB and MAPKs signaling pathways and stimulated SIRT1 expression in psoriasis-like mice." (PMID 33323018, 2021). "Further investigations will be needed to ascertain the potential involvement of NAD+-sirtuin-1-dependent pathway via C/EBPα/π in the regulation of NAMPT expression in psoriasis." (PMID 34202251, 2021). "In a phase IIa clinical study on the efficacy of a SIRT1 activator (SRT2104) in psoriasis, 35% patients showed good to excellent histological improvement, but did not demonstrate a dose-dependent response according to histology endpoints." (PMID 32825671, 2020).
psoriasis (continued). "Based on these studies, SIRT1 activators have been investigated as therapeutic agents for psoriasis; however, the treatment outcomes have been inconsistent." (PMID 32825671, 2020). "The expression of HDAC1 and keratinocyte proliferative markers, such as p63 and PCNA significantly increased, whereas that of SIRT1 decreased in the basal layer (p < 0.05) of the patients with psoriasis compared to those in healthy controls." (PMID 32825671, 2020). "When SRT2014, an agonist of SIRT1, was used to treat moderate to severe psoriasis, it was observed that the expression of known IL-17 and TNF-α responsive genes and that of genes involved in keratinocyte differentiation were significantly downregulated." (PMID 31495284, 2019). "This review aims to elucidate the role of SIRT1 in mediating oxidative stress in psoriasis and to discuss the potential therapeutic role of salidroside in psoriasis." (PMID 31495284, 2019). "SIRT1 is a highly conserved NAD+-dependent histone deacetylase that mediates the antioxidative stress in psoriasis." (PMID 31495284, 2019). "To examine in depth the role of SIRT1 signaling in psoriasis, we performed experiments aimed at highlighting the relationship between SIRT1 and the redox-sensitive MAPK pathway, which has been shown to be altered in psoriasis." (PMID 29799444, 2018). "The present study was undertaken to explore the potential contribution of SIRT-1 signaling to the pathogenetic mechanisms of psoriasis." (PMID 29799444, 2018). "Recently, some authors reported significantly decreased SIRT1 levels in lesional skin from psoriatic samples compared to controls, suggesting its potential involvement in the pathogenesis of psoriasis." (PMID 29799444, 2018). "Our results clearly demonstrate the involvement of SIRT1 in the protective mechanisms related to fibroblast injury in psoriasis." (PMID 29799444, 2018). "Taken together with the finding that SIRT1 activators are effective in attenuating cytokine production, SIRT1 activation offers a potential new approach for treating psoriasis." (PMID 26556603, 2015). "Given the interesting signals of clinical activity, impact on gene expression and the generally favorable safety profile seen in this study, further investigation of SIRT1 activators for the treatment of psoriasis is warranted." (PMID 26556603, 2015). "Our results showed that NMN supplementation might be effective in treating psoriasis patients, especially those with defects in the SIRT1 pathway and NAD+ biosynthesis." (PMID 38397784, 2024). "Psoriasis shows reduced SIRT1-5 expression and increased SIRT6 and SIRT7 expression." (PMID 38892253, 2024). "Emerging evidence suggests that sirtuins, particularly SIRT1, may play a role in the pathogenesis of psoriasis, a chronic inflammatory skin disorder characterized by abnormal immune responses and skin cell proliferation." (PMID 39456475, 2024). "In addition, SIRT1 protects fibroblasts in patients with psoriasis from oxidative-stress-induced apoptosis and reduces MAPK signalling to restore both mitochondrial function and redox balance." (PMID 37445960, 2023). "It has been shown that catalpol can alleviate psoriasis by affecting SIRT1." (PMID 37445960, 2023). "Indeed, our study have highlighted an impaired SIRT1 expression and activity in lesional psoriatic fibroblasts, indicating a role of SIRT1 in the pathogenesis of psoriasis." (PMID 38304233, 2023). "RSV-induced keratinocyte cell death is regulated by the SIRT1/phospho-Akt-dependent signalling pathway, confirming that it may have applications in psoriasis therapy." (PMID 37445960, 2023). "To date, most studies on the role of SIRTs in psoriasis have focused on SIRT1." (PMID 37445960, 2023). "In addition, SIRT1 reduced lesion severity in an Aldara-induced psoriasis model by decreasing STAT3 activation." (PMID 37445960, 2023).
psoriasis (continued). "In this study, we found that glycyrrhizin can attenuate the promotion of p-STAT3 induced by SIRT1, which suggests that glycyrrhizin may be beneficial for improving psoriasis by inhibiting the expression of p-STAT3." (PMID 34044769, 2021). "Together, these results indicate that glycyrrhizin may improve psoriasis by promoting SIRT1 expression and inhibiting STAT3 expression." (PMID 34044769, 2021). "Mechanically, glycyrrhizin inhibits the expression of STAT3 by reversing the inhibitory effect of IL-17A on SIRT1, which may be a potential mechanism by which glycyrrhizin improves psoriasis." (PMID 34044769, 2021). "A previous study reported that oxidative stress contributes to the pathogenesis of psoriasis, and the activation of SIRT1 inhibits the MAPK, NF-κB, and STAT3 oxidative stress signaling pathways, thereby down-regulating inflammatory factors and inhibiting excessive keratinocyte proliferation." (PMID 34044769, 2021). "In summary, our data suggested that catalpol may have a therapeutic property of psoriasis by ameliorating oxidative stress and inflammation partly through SIRT1 mediated suppression of NF-κB and MAPKs pathways." (PMID 33323018, 2021). "The role of SIRT1 in psoriasis is opposite to that of HDAC1." (PMID 32825671, 2020). "SIRT1 is another epigenetic therapeutic target for psoriasis." (PMID 32825671, 2020). "However, only a few studies involving small sample sizes have examined the expression levels of SIRT1 in patients with psoriasis." (PMID 32825671, 2020). "In summary, activation of SIRT1 can counteract the damage caused by oxidative stress by inhibiting the MAPK, NF-κB, and STAT3 pathways, leading to the alleviation of the pathological injury in psoriasis." (PMID 31495284, 2019). "Besides, SIRT1 has been shown to reduce the severity of lesions in the Aldara-induced psoriasis model via negatively regulating STAT3 activation." (PMID 31495284, 2019). "Then, Oxidative stress in psoriasis and the role of SIRT1 were summarized and the potential role of salidroside in the disease was speculated." (PMID 31495284, 2019). "Salidroside, the activator of SIRT1, may cure psoriasis resistant to oxidative stress damage by inhibiting the MAPK, NF-κB, and STAT3 pathways; however, this property of salidroside needs further research." (PMID 31495284, 2019). "Hence, further investigation is required to validate the effects of salidroside on psoriasis pathophysiology and further verify the effect of SIRT1 on MAPK, NF-κB, and STAT3 pathways in the skin." (PMID 31495284, 2019). "Salidroside reportedly plays an antioxidant role via activation of SIRT1, which could serve as a new target for treating psoriasis." (PMID 31495284, 2019). "Moreover, SIRT1 protects fibroblasts of individuals with psoriasis from oxidative stress-induced apoptosis and restores both mitochondrial function and redox balance via downregulation of MAPK signaling." (PMID 31495284, 2019). "In our review, we highlight the role of SIRT1 in reducing oxidative stress in psoriasis." (PMID 31495284, 2019). "On the basis of these observations and of our recent findings, here we demonstrate that, in fibroblasts from lesional psoriatic skin, SIRT1 activity is strongly reduced compared to healthy fibroblasts, suggesting a possible involvement of SIRT1 in the pathogenesis of psoriasis." (PMID 29799444, 2018). "In particular, this is the first study exploring SIRT1 signaling in psoriasis." (PMID 29799444, 2018). "Furthermore, in a recent randomized, double-blind, placebo-controlled Phase IIa study, the effects of a selective small molecule SIRT1 activator in 40 patients with moderate-to-severe psoriasis were investigated." (PMID 29799444, 2018). "Another important consideration must be taken into account: even if fibroblasts and endothelial cells contribute to the pathogenesis of psoriasis, further studies on SIRT1 signaling are also needed on keratinocytes, which display a crucial role in the development of psoriatic lesions." (PMID 29799444, 2018).
psoriasis (continued). "Although length of treatment was more important than type, we could discern that most biologics and even UVB treatment (10 weeks) elicited psoriasis-opposite expression patterns more effectively than treatment with the SIRT1 activator SRT2104." (PMID 26251673, 2015). "In the present study, the treatment of catalpol obviously up-regulated SIRT1 level and inactivated the NF-kB and MAPK pathways in psoriasis conditions in vitro and in vivo, indicating that catalpol may improve the psoriasis-like symptoms via SIRT1 mediated anti-inflammatory effects." (PMID 33323018, 2021). "The dysregulation of this auto-regulatory loop could be also due to the abnormal expression of SIRTs in psoriasis, with the downregulation of SIRT1, SIRT2, SIRT3, SIRT4, and SIRT5 and upregulation of SIRT6 and SIRT7 in skin lesions skin, as previously reported." (PMID 34202251, 2021). "Therefore, SIRT1 can be proposed as a novel molecular target for the treatment of psoriasis." (PMID 29799444, 2018). "Hence, SIRT1 can be proposed as a specific tool for the treatment of psoriasis." (PMID 29799444, 2018). "Modulating SIRT activity using SIRT1-5 agonists and SIRT6-SIRT7 inhibitors is a potential therapeutic option for psoriasis treatment." (PMID 38892253, 2024). "Though few studies on NMN, NAD+, or NADH are directly in relation to psoriasis, the potential of NMN supplementation in preventing and impeding psoriasis development via SIRT1 should be noted." (PMID 38397784, 2024). "Phase II clinical trials of the selective SIRT1 agonist SRT2104 have shown its good efficacy and safety in psoriasis." (PMID 39296901, 2024). "In a mouse model of psoriasis due to IMQ, resveratrol, a SIRT1 agonist, lessens the severity of lesions and histopathological damage." (PMID 39296901, 2024). "According to research, skin biopsy specimens from psoriasis patients have altered SIRT expression, with significantly lower SIRT1 expression than control skin samples." (PMID 39456475, 2024). "A significant decrease in SIRT1 and, conversely, an increase in STAT3 were demonstrated in a mouse model of psoriasis compared with healthy mice." (PMID 37445960, 2023). "There is a significant reduction in the expression of SIRT1, SIRT2, SIRT3, SIRT4 and SIRT5 and an increase in the expression of SIRT6 and SIRT7 in psoriasis." (PMID 37445960, 2023). "Novel research into the anti-aging and anti-inflammatory gene, Sirtuin 1 (SIRT1), has shown decreased levels in patients with MetS, T2DM and psoriasis, further supporting the pro-inflammatory alterations that underly psoriasis." (PMID 35847770, 2022). "Therefore, SIRT1 may regulate the release of inhibitory cytokines by affecting the keratinocyte proliferation and play a key role in the occurrence and development of psoriasis." (PMID 34044769, 2021). "The immunohistochemistry results showed that compared with the skin cells of normal subjects, the skin cells of patients with psoriasis showed substantially increased STAT3 expression and substantially decreased SIRT1 expression." (PMID 34044769, 2021). "The expression of HDAC1, SIRT1, p63, and PCNA was compared between patients with psoriasis and healthy controls using immunohistochemistry." (PMID 32825671, 2020). "Abnormal histone modification by histone deacetylases (HDACs), including HDAC1 and sirtuin 1 (SIRT1), has been reported to play an important role in the pathogenesis of psoriasis by altering cell proliferation, differentiation, and inflammation." (PMID 32825671, 2020). "Moreover, miR-200c and miR-200a both target SIRT1, a key protein involved in oxidative stress and skin inflammation regulation and in the preservation of different biological processes substantially altered in psoriasis, such as proliferation, differentiation, and senescence." (PMID 31929856, 2019). "Recently, a study found that the expression levels of SIRT1-5 were downregulated, while those of SIRT6 and SIRT7 were upregulated in psoriasis skin lesions." (PMID 31495284, 2019).